EIF3J (eukaryotic translation initiation factor 3 subunit J)
Description:
Component of the eukaryotic translation initiation factor 3 (eIF-3) complex, which is required for several steps in the initiation of protein synthesis. The eIF-3 complex associates with the 40S ribosome and facilitates the recruitment of eIF-1, eIF-1A, eIF-2:GTP:methionyl-tRNAi and eIF-5 to form the 43S pre-initiation complex (43S PIC). The eIF-3 complex stimulates mRNA recruitment to the 43S PIC and scanning of the mRNA for AUG recognition. The eIF-3 complex is also required for disassembly and recycling of post-termination ribosomal complexes and subsequently prevents premature joining of the 40S and 60S ribosomal subunits prior to initiation. The eIF-3 complex specifically targets and initiates translation of a subset of mRNAs involved in cell proliferation, including cell cycling, differentiation and apoptosis, and uses different modes of RNA stem-loop binding to exert either translational activation or repression.
Synonyms: EIF3S1; eIF3-p35; eIF3-alpha
Tractability: Small molecule: a structure with a bound ligand is known. PROTAC: UniProt records ubiquitination sites on it; ubiquitination databases record sites on it; its protein half-life has been measured.
Gene: Protein-coding gene on chromosome 15 (44,537,098 to 44,563,029, forward strand). Ensembl gene ENSG00000104131.
Subcellular location: Cytoplasm
Subcellular location (Human Protein Atlas): Cytosol
Pathways (Reactome):
Metabolism of proteins: Formation of a pool of free 40S subunits; Formation of the ternary complex, and subsequently, the 43S complex; GTP hydrolysis and joining of the 60S ribosomal subunit; L13a-mediated translational silencing of Ceruloplasmin expression; Ribosomal scanning and start codon recognition; Translation initiation complex formation
Gene Ontology:
Molecular function: identical protein binding; protein binding; translation initiation factor activity
Biological process: formation of cytoplasmic translation initiation complex; translational initiation; cytoplasmic translational initiation
Cellular component: eukaryotic translation initiation factor 3 complex; cytosol; cytoplasm; eukaryotic 43S preinitiation complex; eukaryotic 48S preinitiation complex
Genetic constraint (gnomAD): Loss-of-function variants: 8 observed, 21.32 expected, observed/expected ratio (o/e) 0.38, 90% interval 0.22 to 0.68. The upper end of that interval is the gene's LOEUF score, 0.68, which puts it in group 2 of 6, group 1 being the genes least tolerant of losing a copy. Missense variants: 161 observed, 197.49 expected, observed/expected ratio (o/e) 0.82, 90% interval 0.72 to 0.93. Synonymous variants: 75 observed, 75.4 expected, observed/expected ratio (o/e) 0.99, 90% interval 0.82 to 1.21.
Homologues: Orthologues: chimpanzee EIF3J (99% identical), macaque EIF3J (99% identical), dog EIF3J (98% identical), pig EIF3J (98% identical), guinea pig EIF3J (97% identical), mouse Eif3j1 (97% identical), mouse Eif3j2 (97% identical), rat Eif3j (97% identical), rabbit EIF3J (78% identical), tropical clawed frog eif3j (68% identical), zebrafish eif3ja (65% identical), zebrafish eif3jb (62% identical), and 2 more.
Diseases named in the same sentence as EIF3J in open-access papers:
EIF3J is named in the same sentence as 10 diseases in open-access papers, as found by Europe PMC text mining. Sharing a sentence is not in itself a finding about the gene and the disease. The quoted sentences say what the papers report.
breast carcinoma (2 papers, 2021 to 2022). "And a higher transcriptional level of EIF3J and EIF3K was associated with advanced pathologic grades and poor outcomes for breast cancer patients." (PMID 35040374, 2022). "In our report, EIF3G/ K/ L was down-regulated in breast cancer tissues compared with normal tissues, while EIF3J presented the opposite trend." (PMID 35040374, 2022).
cervical carcinoma (2 papers, 2020 to 2024). A carcinoma arising from either the exocervical squamous epithelium or the endocervical glandular epithelium. "For example, the knockdown of circRNA-EIF3J in human cervical carcinoma HeLa cells significantly decreases the expression of Eukaryotic translation initiation factor 3J (EIF3J) mRNA." (PMID 39062737, 2024). "It has been demonstrated that circ-EIF3J, circ-PAIP2, and circ-FUNDCl are significantly overexpressed in cervical cancer cells." (PMID 33312941, 2020).
epilepsy (1 paper, 2020). A brain disorder characterized by episodes of abnormally increased neuronal discharge resulting in transient episodes of sensory or motor neurological dysfunction, or psychic dysfunction. "There is no obvious relationship between the identified hub genes and the lipid metabolism, e.g., EIF3J (eukaryotic translation initiation factor 3 subunit J), EPM2A (epilepsy, progressive myoclonus type 2A), and CALM1 (calmodulin 1)." (PMID 33117416, 2020).
schizophrenia (1 paper, 2024). A major psychotic disorder characterized by abnormalities in the perception or expression of reality. "Additionally, EIF3J has been implicated in the development of positive symptoms in schizophrenia, potentially through regulatory mechanisms in peripheral blood." (PMID 39716063, 2024).
cancer (3 papers, 2019 to 2025). A tumor composed of atypical neoplastic, often pleomorphic cells that invade other tissues. "In blood of girls with high genistein concentrations in their urine, two proteins associated with cancer were down regulated: endothelin-converting enzyme (ECE-1) and eukaryotic translation initiation factor 3 subunit J (EIF-3)." (PMID 33330580, 2020). "Levels of nine eIF3 subunits involving eIF3A, eIF3B, eIF3C, eIF3D, eIF3E, eIF3H, eIF3I, eIF3J, and eIF3M were significantly increased in cancer tissues, whereas the eIF3L expression level in tumours was independently decreased than that of normal tissues (p < 0.05)." (PMID 31885740, 2019). "These included RPL6, RPL7, RPL18A, RPS2, EIF3E, EIF3J, and UBA52, reflecting the elevated protein synthesis demands of cancer cells." (PMID 41228302, 2025).
tumor (3 papers, 2019 to 2023). "And high expression of eIF3E and eIF3J was observed more in patients with residual tumours (13/4 vs. 172/170, p = 0.0456) and without mutations in KRAS/EGFR/ALK (47/48 vs. 86/46, p = 0.0206), respectively." (PMID 31885740, 2019). "Besides, nine eIF3 subunits beyond eIF3D were found aberrantly expressed in LUAD tissues and in which the expression levels of five subunits (eIF3B, eIF3C, eIF3E, eIF3H, and eIF3J) increased in LUAD patients with high tumour stage, implicating their roles in the maintenance or progression of LUAD." (PMID 31885740, 2019). "Difference is found in the expression of EIF3A, EIF3B, EIF3D, EIF3F, EIF3H, EIF3J, and EIF3M in different tumor stages." (PMID 36051357, 2022).
psychiatric disorder (1 paper, 2024). A disorder characterized by behavioral and/or psychological abnormalities, often accompanied by physical symptoms. "Genome-wide association studies from the Psychiatric Genetics Consortium and analysis of ONE cells from SCZ patients also show alterations in the EIF pathway, underscoring the role of EIF3J in psychiatric disorders." (PMID 39716063, 2024).
EIF3J also shares sentences with these, for which no sentence is quoted: lymph node metastasis (1 paper); neuromuscular disease (1); viral infection (1).